ZNF177 (zinc finger protein 177)
Description:
May be involved in transcriptional regulation.
Tractability: PROTAC: ubiquitination databases record sites on it.
Gene: Protein-coding gene on chromosome 19 (9,363,013 to 9,382,617, forward strand). Ensembl gene ENSG00000188629.
Subcellular location: Nucleus
Gene Ontology:
Molecular function: protein binding; sequence-specific double-stranded DNA binding; DNA-binding transcription factor activity, RNA polymerase II-specific; RNA polymerase II transcription regulatory region sequence-specific DNA binding
Biological process: negative regulation of transcription by RNA polymerase II; regulation of transcription by RNA polymerase II; regulation of DNA-templated transcription
Cellular component: blood microparticle; nucleus
Genetic constraint (gnomAD): Loss-of-function variants: 19 observed, 20.92 expected, observed/expected ratio (o/e) 0.91, 90% interval 0.63 to 1.33. The upper end of that interval is the gene's LOEUF score, 1.33, which puts it in group 5 of 6, group 1 being the genes least tolerant of losing a copy. Missense variants: 633 observed, 588.72 expected, observed/expected ratio (o/e) 1.08, 90% interval 1.01 to 1.15. Synonymous variants: 220 observed, 197.71 expected, observed/expected ratio (o/e) 1.11, 90% interval 1 to 1.24.
Homologues: Orthologues: chimpanzee ZNF177 (99% identical), macaque ZNF177 (94% identical), dog ZNF177 (78% identical), pig ZNF177 (77% identical), Drosophila melanogaster CG3281 (24% identical), Drosophila melanogaster Phs (22% identical), Drosophila melanogaster CG2712 (22% identical). Paralogues in human: ZNF559 (44% identical), ZNF560 (44% identical), ZFP37 (42% identical), ZNF555 (42% identical), ZNF20 (41% identical), ZNF77 (41% identical), ZNF266 (41% identical), ZNF674 (41% identical), ZNF264 (40% identical), ZFP90 (40% identical), ZNF805 (40% identical), ZNF69 (40% identical), and 50 more.
Diseases named in the same sentence as ZNF177 in open-access papers:
ZNF177 is named in the same sentence as 20 diseases in open-access papers, as found by Europe PMC text mining. Sharing a sentence is not in itself a finding about the gene and the disease. The quoted sentences say what the papers report.
breast carcinoma (5 papers, 2021 to 2023). "Indeed, ZNF177 is part of the signature of hypermethylated genes of diagnostic value in early stages of lung and breast cancer." (PMID 33917510, 2021). "Results from additional validation analyses showed that MAST1, PRDM14, and ZNF177 had high sensitivity, specificity, and accuracy for breast cancer diagnosis." (PMID 33499882, 2021). "In summary, we have identified and independently validated abnormal DNA methylation patterns in MAST1, PRDM14, and ZNF177 as potential biomarkers for breast cancer diagnosis." (PMID 33499882, 2021). "Overall, we found that MAST1, PRDM14, and ZNF177 had high sensitivity, specificity, and accuracy for the diagnosis of breast cancer." (PMID 33499882, 2021). "As expected, methylation levels of ADCY4, CPXM1, DNM3, GNG4, MAST1, PRDM14, and ZNF177 were found to be increased in breast cancer, and all with p values lower than 0.001." (PMID 33499882, 2021). "To further explore the clinical value of these biomarkers, we evaluated whether 6 of our differentially methylated genes—ADCY4, CPXM1, DNM3, PRDM14, PRKCB, and ZNF177—had any relation with overall survival of breast cancer patients." (PMID 33499882, 2021). "Methylation pattern of MAST1, PRDM14, and ZNF177 may represent new diagnostic biomarkers for breast cancer, while methylation of ADCY4, CPXM1, DNM3, PRDM14, PRKCB, and ZNF177 may hold prognostic potential for breast cancer." (PMID 33499882, 2021). "Moreover, we showed that DNA methylation landscape of ADCY4, CPXM1, DNM3, PRDM14, PRKCB, and ZNF177 could be selected as accurate biomarkers for the prognosis of breast cancer." (PMID 33499882, 2021). "However, the role of MAST1, PRDM14, and ZNF177 in diagnosis and prognosis of breast cancer remains unclear." (PMID 33499882, 2021). "Aberrant methylation of CCDC181, GCM2, ITPRIPL1, ENPP2, LOC643719, ZNF177 and ADCY4 was found in breast cancer patients from the Taiwanese and TCGA cohorts using the methylation array." (PMID 33803633, 2021). "The methylation patterns of the CCDC181, GCM2, ITPRIPL1, ENPP2, LOC643719, ZNF177 and ADCY4 genes were further determined in plasma samples from healthy and early breast cancer patients." (PMID 33803633, 2021). "The results for seven candidate genes—CCDC181, GCM2, ITPRIPL1, ENPP2, LOC643719, ZNF177 and ADCY4—were successfully validated by sequencing and stable detection in ccfDNA from the plasma of Taiwanese patients with breast cancer." (PMID 33803633, 2021). "The breast cancer specificity of methylated CCDC181, GCM2, ITPRIPL1, LOC643719 and ZNF177 ranged from 64.3 to 100%, indicating lower false-positive signals." (PMID 33803633, 2021). "Aberrant methylation patterns of the CCDC181, GCM2, ITPRIPL1, ENPP2, LOC643719, ZNF177 and ADCY4 genes were identified and further evaluated in paired tumor and normal tissues of breast cancer patients." (PMID 33803633, 2021). "To further determine the methylation pattern of breast cancer tissues in the Taiwanese cohort, we analyzed the methylation levels of CCDC181, GCM2, ITPRIPL1, ENPP2, LOC643719, ZNF177 and ADCY4 in tumors and adjacent normal tissue in Taiwanese breast cancer patients." (PMID 33803633, 2021). "Our findings add a new layer of evidence to the epigenetic landscape of breast cancer, providing convincing clues that MAST1, PRDM14, and ZNF177 are differentially methylated in breast cancer, as well as that they may serve as potential drivers and biomarkers for breast cancer." (PMID 33499882, 2021).
gastric cancer (2 papers, 2021). A primary or metastatic malignant neoplasm involving the stomach. "ZNF177 is methylation-silenced in gastric cancer cell lines, whereas methylation of its promotor is a frequent epigenetic event in endometrial cancer." (PMID 33499882, 2021). "SORCS3, ZNF154 and ZNF177 are hypermethylated in gastric cancers, while ZNF177 is also hypermethylated in hepatocellular carcinomas." (PMID 34882728, 2021).
bladder cancers (1 paper, 2019). "Additionally, the promoter-hypermethylations of LMX1A, SOX1, and ZNF177 were previously reported in lung, stomach, and bladder cancers, respectively, by other groups." (PMID 31547144, 2019).
cervical tumors (1 paper, 2021). "Interestingly, a higher level of ZNF177 was found in BLs than in cervical tumors, HSILs, and SCCCs, suggesting that there is an inverse relationship with miR-877-3p expression." (PMID 33917510, 2021). "Importantly, we noticed that cytoplasmic ZNF177 levels were significantly higher in cervical tumors than in BLs." (PMID 33917510, 2021).
colon adenocarcinoma (1 paper, 2019). "Moreover, the correlation analysis of the differential methylation and expression levels of LMX1A, SOX1, ZNF177 and NKX6.1 in colon adenocarcinoma patients was based on data derived from the MethHC database." (PMID 31547144, 2019).
colorectal cancer (1 paper, 2020). A primary or metastatic malignant neoplasm that affects the colon or rectum. "We also found that LMX1A, in combination with NKX6.1, SOX1, and ZNF177, could serve as a stage-independent prognostic marker in colorectal cancer." (PMID 32751497, 2020).
endometrial carcinoma (1 paper, 2021). A malignant tumor arising from the epithelium that lines the cavity of the uterine body. "Several reports have also shown that methylation of ZNF177 is associated with different types of cancer including gastric and endometrial cancers, as well as non-small cell lung carcinoma." (PMID 33499882, 2021). "Indeed, ROC analysis of ZNF177 has demonstrated that it can identify endometrial carcinomas cases with a sensitivity, specificity, and accuracy of 92.3%, 94.4%, and 95.1%, respectively." (PMID 33499882, 2021).
gynecological cancers (1 paper, 2021). "Of all the predicted targets, the zinc finger protein 177 (ZNF177) gene was selected because it has been described as being epigenetically silenced in other tumor types, including gynecological cancers." (PMID 33917510, 2021).
metastatic tumors (1 paper, 2025). "While the transcriptomic alterations were generally limited, in bone and lung metastatic tumors, the AA genotype was enriched with SEBOX and ZNF177 expression." (PMID 40282446, 2025).
squamous cell carcinomas of the cervix (1 paper, 2021). "Interestingly, miR-877-3p downregulated the levels of an in silico-predicted target, ZNF177, whose expression and subcellular location significantly distinguished high-grade squamous intraepithelial lesions (HSILs) and squamous cell carcinomas of the cervix (SCCCs)." (PMID 33917510, 2021).
cancer (4 papers, 2019 to 2021). A tumor composed of atypical neoplastic, often pleomorphic cells that invade other tissues. "A few cancer types are known to exhibit epigenetic inhibition of ZNF177 expression." (PMID 33917510, 2021).
tumor (3 papers, 2019 to 2021). "We found a statistically significant association between LMX1A methylation and tumor size (p = 0.0048) but did not observe significant associations between SOX1 or ZNF177 methylation and any of the clinicopathological parameters." (PMID 31547144, 2019).
ZNF177 also shares sentences with these, for which no sentence is quoted: Fibroadenoma (1 paper); hepatocellular carcinoma (1); lung (1); lung carcinoma (1); non-small cell lung carcinoma (1); ovarian carcinoma (1); rectal adenocarcinoma (1); squamous intraepithelial lesions (1).